IER3 (immediate early response 3)
Diseases named in the same sentence as IER3 in open-access papers (continued):
Sharing a sentence is not in itself a finding about the gene and the disease.
melanoma (2 papers, 2019 to 2023). A malignant, usually aggressive tumor composed of atypical, neoplastic melanocytes. "In conclusion, we reported the association of HRGs with patient prognosis in melanoma and screened for novel gene signatures, including FBP1, NDRG1, GPI, IER3, B4GALNT2, BGN, PKP1, and EDN2." (PMID 37422626, 2023).
pancreatic ductal adenocarcinoma (2 papers, 2016 to 2019). An infiltrating adenocarcinoma that arises from the epithelial cells of the pancreas. "Interestingly, IER3 has been shown in pancreatic ductal adenocarcinoma to effectively mitigate against cellular stress induced by starvation or exposure to gemcitabine." (PMID 31242667, 2019). "As a member of the NUPR1/RELB/IER3 survival pathway, may provide pancreatic ductal adenocarcinoma with remarkable resistance to cell stress, such as starvation or gemcitabine treatment." (PMID 27767172, 2016).
prostate carcinoma (2 papers, 2005 to 2023). A carcinoma that arises from epithelial cells of the prostate gland. "Of particular interest are: FGF9 which may stimulate the growth of prostate cancer, brain cancer and endometrium; and IER3 (IEX-1), PHLDA2 (TSS3), IAPP (amylin), and SST, all of which may play roles in apoptosis." (PMID 15691381, 2005). "Among CHD1 target genes, immediate early response 3 (IER3), leukemia inhibitory factor (LIF), and colony stimulating factor 2 (CSF2) were significantly correlated with ESS2 expression in patients with prostate cancer." (PMID 37524814, 2023).
Sepsis (2 papers, 2016 to 2024). Sepsis is defined as life-threatening organ dysfunction caused by a dysregulated host response to infection. "Harnessing the expression profiles of pivotal glycolytic genes: PPARG, DSC2, and IER3: we’ve devised a predictive model that seeks to revolutionize the diagnostic approach to sepsis." (PMID 39331858, 2024). "While our findings build on this knowledge, they pave the way for further exploration, particularly in evaluating the therapeutic potential of modulating IER3 in conditions like sepsis and IBD." (PMID 39331858, 2024). "In conclusion, our exploration underscores the pivotal role of glycolysis in sepsis, emphasizing the significance of IER3, DSC2, and PPARG." (PMID 39331858, 2024). "Among the myriad genes, IER3, DSC2, and PPARG emerged as linchpins, their prominence in sepsis further validated through ROC analytics." (PMID 39331858, 2024). "In line with our endeavor to “unveil the glycolysis in sepsis,” the discovery of IER3, DSC2, and PPARG reinforces their cardinal roles in sepsis pathogenesis." (PMID 39331858, 2024). "In our exploration, we identify a clear linkage between key glycolytic genes, IER3 and DSC2, and the behavior of neutrophils during sepsis." (PMID 39331858, 2024).
AIDS (1 paper, 2019). A syndrome resulting from the acquired deficiency of cellular immunity caused by the human immunodeficiency virus (HIV). "We propose that the coordinated upregulation of CDKN1A, IER3, GADD45B and TNF as well as the positive regulation of calcium-dependent signaling could be involved in the mechanisms leading to the slower progression to AIDS and HIV control concomitantly observed in EC-LTNPs." (PMID 31582776, 2019).
autoimmune disease (1 paper, 2025). A disorder resulting from loss of function or tissue destruction of an organ or multiple organs, arising from humoral or cellular immune responses of the individual to their own tissue constituents. "Our Bayesian colocalization analysis revealed five genes, including GTF2H4, FLOT1, HCP5, immediate early response 3 (IER3), and serine/threonine kinase 19 (STK19), that were identified as having a shared variant with autoimmune diseases (PP.H4 > 0.8)." (PMID 40599891, 2025).
bone marrow failure syndrome (1 paper, 2015). "Although there is no experimental evidence to support this notion in patients yet, it is interesting to note that various IER3 perturbations have been found in MDS patients and that Ier3 knock-out mice develop a bone marrow failure syndrome with MDS-like features." (PMID 25569081, 2015).
Bovine mastitis (1 paper, 2025). INFLAMMATION of the UDDER in cows. "In conclusion, this study highlights the essential role of YTHDF2 and IER3 in the inflammatory response of bovine mammary cells to S. aureus infection, providing novel insights into the molecular mechanisms underlying bovine mastitis." (PMID 40521032, 2025).
epilepsy (1 paper, 2026). A brain disorder characterized by episodes of abnormally increased neuronal discharge resulting in transient episodes of sensory or motor neurological dysfunction, or psychic dysfunction. "What's more, the dysregulation of TNF and IER3 pathways in PM‐associated epilepsy suggests therapeutic potential for targeted immunomodulation (e.g., TNF signaling blockade), which may mitigate seizure susceptibility in high‐risk patients." (PMID 41466027, 2026). "The differential expression of four DE‐SRGs between control and epilepsy groups, including IER3, TNF, GPANK1 (upregulated), and ATF6B (downregulated), further elucidates the molecular mechanisms underlying the epilepsy phenotype." (PMID 41466027, 2026). "Our findings add to the body of evidence suggesting that targeting immune pathways, particularly those involving TNF and IER3, may offer therapeutic benefits in epilepsy management." (PMID 41466027, 2026). "PCR results show the expression of IER3, TNF, GPANK1, and ATF6B in hippocampus of epilepsy model largely consistent with bioinformatics predictions." (PMID 41466027, 2026). "IER3, an immediate early response gene, is known for its role in the regulation of immune and inflammatory responses, but its role in epilepsy has not been reported, which deserves further study." (PMID 41466027, 2026). "Finally, the expression of four key genes (IER3, TNF, GPANK1, and ATF6B) in the hippocampus of epilepsy mouse model was quantified using PCR." (PMID 41466027, 2026). "Finally, although we validated the altered expression of IER3, TNF, GPANK1, and ATF6B in multiple epilepsy models, we did not investigate the correlation between their expression levels and behavioral seizure outcomes (e.g., Racine scores, seizure frequency)." (PMID 41466027, 2026).
Ewing sarcoma (1 paper, 2013). A small round cell tumor that lacks morphologic, immunohistochemical, and electron microscopic evidence of neuroectodermal differentiation. "Importantly, successive steps allowed to identify novel players involved in Ewing sarcoma such as CUL1 or CFLAR or IER3." (PMID 23935076, 2013). "Because IER3 is a modulator of apoptosis through TNFalpha or FAS-signaling, the balance between its repression (through MYC, E2F2 and E2F5 that are EWS-FLI1 induced and therefore disease specific) and activation (through NFkB) may be of particular interest in Ewing sarcoma." (PMID 23935076, 2013).
glioma (1 paper, 2015). A benign or malignant brain and spinal cord tumor that arises from glial cells (astrocytes, oligodendrocytes, ependymal cells). "In contrast, expression of the Ier3 (Immediate early response 3) gene, which enhances apoptosis in radiated glioma cells via NFkB, MAPK/ERK and PI3K/Akt signaling, was increased in co-cultured U373 cells." (PMID 26517510, 2015).
inflammatory bowel disease (1 paper, 2022). A spectrum of small and large bowel inflammatory diseases of unknown etiology. "For example, IER3 is known to play a role in inflammatory bowel disease and following Leishmania infection, whereas NR4A1 modulates apoptosis of monocytes." (PMID 35082159, 2022).
lung squamous cell carcinoma (1 paper, 2024). "For lung squamous cell carcinoma, 11 genes were causally related, comprising COPA, NCSTN, U91328.19, GABBR1, IER3, HLA-DQB1-AS1, HLA-DQB2, ANKRD26, PKD2L1, PSMA4 and RAD51C." (PMID 38834983, 2024).
ovarian tumors (1 paper, 2025). "Inordinately elevated IL-6 may drive, via the IL6/IER3 signaling axis, chemoresistance and disease recurrence of ovarian tumors; higher levels of IL-6 and VEGA-A were significantly associated with shorter progression-free survival." (PMID 40507922, 2025).
psoriasis (1 paper, 2011). An autoimmune condition characterized by red, well-delineated plaques with silvery scales that are usually on the extensor surfaces and scalp. "In addition, we found that SNPs from several non-HLA genes including rs2251396, rs2523454 and rs12175589 in MICA, rs7770216 in LOC729816, rs511027 in NOTCH4, rs9257483 in OR12D2 and 9262167 in IER3 were associated with psoriasis in multiple regression analyses." (PMID 22125590, 2011). "In addition to classical HLA genes such as HLA-C, HLA-B and HLA-DQA2, we also find association of non-HLA genes in the MHC region such as POU5F1, NFKBIL1, NOTCH4, MICA, IER3 and OR12D2 with psoriasis." (PMID 22125590, 2011).
sarcoidosis (1 paper, 2020). Sarcoidosis is a multisystemic disorder of unknown cause characterized by the formation of immune granulomas in involved organs. "For example, here, among other genes, STAT1, IL10RA, and PTEN were underexpressed in sarcoidosis CD14 monocytes compared to controls while CXCR4, ATG12, HIF1A, CCR1, and IER3 were overexpressed, consistent with the effects of TGFB1 signaling." (PMID 33363531, 2020).
squamous carcinomas (1 paper, 2018). "IER3 was initially identified as a radiation-inducible protein in squamous carcinomas." (PMID 30249226, 2018).
T-cell lymphoma (1 paper, 2016). "Mice overexpressing IER3 spontaneously developed T-cell lymphoma, likely due to altered apoptosis sensitivity (including susceptibility to death receptor ligation), cell cycle progression, and/or proliferation." (PMID 27767172, 2016).
Thrombocytopenia (1 paper, 2025). A reduction in the number of circulating thrombocytes. "PPP2R5C interacts with IER3, and the deletion of IER3 can lead to platelet and RBC defects, accompanied by thrombocytopenia." (PMID 39331630, 2025).
cancer (29 papers, 2016 to 2025). A tumor composed of atypical neoplastic, often pleomorphic cells that invade other tissues. "Despite its significance in cancer development, there is a dearth of studies elucidating the exact mechanisms underlying IER3's involvement in modulating cancer behavior." (PMID 40090972, 2025). "In present study, we determined that IER3 protein was overexpressed in the cytoplasm of cancer cells in BCa tissues specimens and that high IER3 protein expression was distinctly associated with high pathologic nodal stage." (PMID 30249226, 2018). "The IER3 gene has a complex role in cancer biology, acting either as a tumor suppressor or an oncogene, depending on the cancer type." (PMID 40090972, 2025). "Mounting evidence suggests that IER3 can exert either promoting or inhibitory effects on cancer development in various types of malignancies." (PMID 39602465, 2024). "Mostly studied in cancer cells, several functions have been attributed to IER3, including effects on apoptosis, inflammation and regulation of mitochondrial respiration." (PMID 38528525, 2024). "Increasing evidence suggests that IER3 functions either as an oncogene or as a tumor suppressor in various human cancers." (PMID 36982814, 2023). "By functionality, we grouped genes according to their function: regulator of energy metabolism (Gadd45a), apoptosis (Bcl2, Ier3), catabolic processes (Zfand2a), inflammation (Klkb1, Tnfrsf14), cell cycle control, and cancer (Csnk2a1, Cdc42, Rasa1, Prdx2, Tpr)." (PMID 36982814, 2023). "Although the role of IER3 in some cancers has been reported, the role of IER3 in HCC requires further exploration." (PMID 35291486, 2022). "To date, a few related studies have shown that IER3 can be used as a biomarker for cancer prognosis." (PMID 35291486, 2022). "Growing evidence shows that IER3 functions either as an oncogene or a tumor suppressor in various human cancers with a cancer type-dependent manner." (PMID 30249226, 2018). "There are also a growing number of reports suggesting the involvement of IER3 in cancer and inflammatory diseases." (PMID 27256408, 2016). "Thus, our findings uncover the molecular pathways that dictate the context-dependent roles of IER3 in cancer, providing insights into its dual functionality in different cancer types." (PMID 40090972, 2025). "Previous studies have shown that IER3 expression in cancer is significantly reduced, and overexpression of IER3 could promote the apoptosis of cancer cells and enhance its sensitivity to chemotherapeutic drugs." (PMID 33472635, 2021). "IER3 (immediate early response 3) and HIF1A (hypoxia-inducible factor 1-alpha) transcriptionally regulate glycolytic genes s promoting a Warburg-like glycolytic shift in cancer cells." (PMID 41171083, 2025). "Noteworthy enrichment pathways included “Negative Regulation of the PI3K/Akt Network”, “PI3P, PP2A, and IER3 Regulate PI3K/AKT Signalling”, and “PI3K/AKT Signalling in Cancer”." (PMID 38790263, 2024). "IER3 (immediate early response 3) and HIF1A (hypoxia-inducible factor 1-alpha) transcriptionally regulates glycolytic genes glycolytic genes promoting a Warburg-like glycolytic shift in cancer cells." (PMID 40475528, 2025). "The functional enrichments suggested potential interactions with five pathways mediated by AKT signaling such as PI3K/AKT signaling in cancer, PIP3 activates AKT signaling, AKT phosphorylates targets in the nucleus and PI5P PPA and IER3 regulate PI3K/AKT signaling." (PMID 39950162, 2025). "Furthermore, they are associated with Receptor Tyrosine Kinase signaling (p = 2.36E−9), long-term potentiation (p = 2.15E−5), PI3K/AKT signaling in cancer (p = 5.82E−5), and regulation of PI3K/AKT signaling by PI5P, PP2A, and IER3 (p = 6.78E−5)." (PMID 37303738, 2023).
cancer (continued). "The first five core paths of COVID-PF are IL-10 signaling; constitutive signaling by aberrant PI3K in cancer; PI3K/AKT signaling in cancer; PI5P, PP2A, and IER3 regulate the PI3K/AKT signaling; and transcriptional regulation by the AP-2 (TFAP2) family of transcription factors." (PMID 33768100, 2021). "Also, many cancer-related genes such as IL7, S100B and IER3 showed an altered expression pattern." (PMID 28325946, 2017).
tumor (20 papers, 2007 to 2025). "Cells in Mac_0 were characterized by expression of complement-related genes (C1qa, C1qb, C1qc) and cytokines (Spp1, Ccl12), while cells in Mac_1 expressed higher levels of several tumor-associated macrophage-related genes such as Arg1, Cebpb, and Ier3." (PMID 34030676, 2021). "Taken together, these results suggest that the in vivo antitumor efficacy of AEZS-136 is associated with tumor cell death, resulting from decreased IER3 expression in tumor cells." (PMID 27767172, 2016). "The expression of IER3 in HCC was related to tumor progression; however, the precise mechanisms underlying the regulation by IER3 of the occurrence and development of HCC remain unknown." (PMID 35291486, 2022). "Subsequent studies revealed a significant positive causal relationship for the IER3 gene, suggesting its critical regulatory role in CRC development, particularly through modulating intercellular signaling within the tumor microenvironment." (PMID 40806320, 2025). "Aberrant expression of IER3 has been observed in certain cancers, where it regulates tumor cell proliferation, invasion, and metastasis, contributing to tumorigenesis, progression, and prognosis." (PMID 40299640, 2025). "Studies have shown that IER3 is involved in biological processes such as cell proliferation, apoptosis, and tumor cell invasion and metastasis by regulating multiple signaling pathways, some of which are closely related to bone formation." (PMID 40299640, 2025). "IER3 was a presumed tumor suppressor in the cervix, and the c-Ab1/p73beta/IER3 axis is a new key signaling pathway that endows etoposide with chemosensitivity." (PMID 35291486, 2022). "We next assessed the ability of TRAIL/IER3 synergistic effect in HCC cells to impact in vivo tumor growth." (PMID 33472635, 2021). "After 24 days, we found that tumors in which TRAIL and IER3 had been overexpressed were significantly smaller than control tumors in these animals, consistent with observed differences in tumor growth curves between groups." (PMID 33472635, 2021). "In order to assess how IER3 expression is associated with HCC patient survival, we examined the expression of this protein via IHC in HCC patient tumor microarrays (TMAs)." (PMID 33472635, 2021). "According to our in vitro data, tumor necrosis and IER3 downregulation were shared only by cell death-sensitive AEZS-136 cells, suggesting a key role of IER3 in AEZS-136-iduced resistance." (PMID 27767172, 2016). "IER3 dependent tumor suppressor pathway in NB cells relies on ADAM19 gene." (PMID 40090972, 2025). "Using the TCGA and GTEx data, we could learn the expression of five genes of the TEXPM construct, FTL, GZMA, CD14, and NPC2 were highly expressed in tumor tissues, and IER3 was highly expressed in paracancerous tissues." (PMID 37354485, 2023). "In contrast to the epithelial cells, carboplatin treatment led to increased expression of pro-survival factors (Bcl2, Mcl1, Ier3, Ier5, Hmox1) in stromal cell populations, thus preserving their viability and potentially providing a means of stabilizing and prolonging the anti-tumor response." (PMID 37660083, 2023). "However, there is also evidence that IER3 can promote the apoptotic death of HeLa and 293 tumor cells under serum starvation conditions." (PMID 33472635, 2021). "The role of IER3 in regulating tumor cell growth is highly controversial." (PMID 27336713, 2016). "Collectively, our data suggested that IER3 expression in tumor samples after AEZS-136 treatment might serve as a biomarker of treatment response allowing the identification of AEZS-136 unresponsive patients treatment." (PMID 27767172, 2016).
tumor (continued). "However, within the established tumor microenvironment, IER3 upregulation in specific epithelial cell subpopulations (SSCs) may represent an adaptive response that enhances cellular survival and promotes tumor progression." (PMID 40806320, 2025). "IER3 may, nevertheless, be used as a target for promoting the chemosensitivity of tumor therapy." (PMID 35291486, 2022). "Moreover, IER3 were found to play crucial roles in regulating tumor growth." (PMID 30249226, 2018). "To confirm that IER3 was expressed in CAFs, we used antibodies against IER3 and collagen type III α 1 chain (COL3A1, a marker of fibroblast) to stain a subset of tumor specimens from cohort 3 (19 samples from 11 patients)." (PMID 37424047, 2023). "The higher level of IER3 in RNA-seq and clinicopathological parameters were positively correlated with pathologic grade (G3-G4), pathologic stage (III–IV), new tumor event after initial treatment (yes), and alcohol history." (PMID 35291486, 2022). "We analyzed IER3 expression levels in HCC tissues and tumor adjacent normal (TAN) tissues, and IHC analysis revealed that IER3 expression was undetectable or found to be only expressed at low levels in HCC cases compared with TAN." (PMID 33472635, 2021). "Based on mIF staining signals, we found that proportions of IER3+ CAFs were higher in tumor samples from on‐treatment and nonresponder group." (PMID 37424047, 2023). "However, more IER3+ CAFs accumulated near NRG1+ malignant cells in tumor specimens from nonresponders." (PMID 37424047, 2023).